SDHB (succinate dehydrogenase complex iron sulfur subunit B)
Diseases named in the same sentence as SDHB in open-access papers (continued):
Sharing a sentence is not in itself a finding about the gene and the disease.
neuroendocrine tumors (11 papers, 2012 to 2025). "Loss of SDHB in this case remained unexplained and represents a further confusing factor with neuroendocrine neoplasms." (PMID 34228212, 2022). "The alkylating agent temozolomide has also shown promise in treating metastatic neuroendocrine tumors, with one study reporting a 70% reduction in tumor size in a SDHB-mutation-positive patient." (PMID 33564614, 2021). "A correlation between SDHB expression loss, increased Ki-67 labeling index and biological aggressiveness was shown in advanced midgut neuroendocrine tumors, suggesting a role of tumor suppressor gene." (PMID 24213468, 2012). "Thirty-one consecutive, advanced primary midgut neuroendocrine tumors and related lymph node or liver metastases from 24 males and seven females were immunohistochemically assessed for SDHB." (PMID 24213468, 2012). "Long-term clinical follow-up include genetic background analysis such as SDHB, SDHD, VHL, and RET, required in view of the metastatic potential of this rare neuroendocrine tumor." (PMID 41426338, 2025).
pituitary adenomas (11 papers, 2015 to 2025). "Mutations in mitochondria-related genes, such as SDHB, have been identified in pituitary adenomas, highlighting the significance of genetic and epigenetic changes in their pathogenesis." (PMID 39765842, 2024). "The familial association of pituitary adenomas with PPGLs (both adrenal and extra-adrenal) has been described, dubbed “3PA”; and has been found to have an association with both SDHB and SDHD mutations." (PMID 28965289, 2017). "They identified missense mutations in SDHB (c.487T>C, p.Ser163Pro) and SDHD (c.149A>G, p.His50Arg; c.53C>T, p.Ala18Val) among patients with sporadic pituitary adenomas." (PMID 39765842, 2024). "Other rare tumours found in SDHB carriers are thyroid tumors, pituitary adenoma, parathyroid adenoma and pulmonary carcinoid tumour." (PMID 34181326, 2021). "All pituitary adenomas showed intact staining for both SDHA and SDHB." (PMID 32252027, 2020).
renal carcinoma (11 papers, 2015 to 2025). A carcinoma arising from the epithelium of the renal parenchyma or the renal pelvis. "The majority of SDH-deficient renal cancers involve mutations in SDHB, and these tumors can similarly behave aggressively with early age of onset." (PMID 36128328, 2022). "Vacuoles have been described in SDHB mutation-related renal carcinoma and were attributed to giant mitochondria, but the clear cytoplasm observed in these tumors can also represent glycogen or fat." (PMID 25494863, 2015). "Although no clear-cut genotype–phenotype correlations have been defined, it is interesting to note that four unrelated subjects who developed renal cancer all harboured the same SDHB splice site mutation (c.423+1G>A), and that two of these subjects developed multifocal disease." (PMID 26273102, 2015). "In addition, germline loss-of-function mutations of the TCA cycle enzyme genes, including FH, SDHB, SDHC, and SDHD, have been identified in renal cancers that appear to have an increased risk for more aggressive tumors." (PMID 34609963, 2021). "In SDHB mutated renal cancers, immunohistochemistry for SDHB is negative." (PMID 26273102, 2015).
ovarian carcinoma (9 papers, 2014 to 2023). A malignant neoplasm originating from the surface ovarian epithelium. "However, the role of SDHB in ovarian carcinoma tumourigenesis, especially its association with cellular proliferation, invasion, and migration are not fully elucidated." (PMID 25491408, 2014). "It has been observed that the knockdown of SDHB (succinate dehydrogenase subunit B) results in EMT in mouse ovarian cancer cells and histone hypermethylation, leading to metabolic vulnerability." (PMID 36358644, 2022). "We found that SDHB silencing promoted ovarian cancer invasion and migration accompanied with up-regulated expression of MMP-2 and p-FAK." (PMID 25491408, 2014). "SDHB mRNA and protein was decreased in human ovarian carcinoma compared with normal ovarian epithelium." (PMID 25491408, 2014). "Our data suggested that SDHB plays an essential role in ovarian cancer cell proliferation, invasion, migration and apoptosis via AMPK-HIF-1α pathway." (PMID 25491408, 2014). "SDHB mRNA and protein level was significantly down regulated in human ovarian carcinoma compared with the controls." (PMID 25491408, 2014). "Of 211 ovarian cancer samples that had sufficient stromal and epithelial components for evaluation, seven samples exhibited significantly decreased levels of SDHB in tumor epithelia relative to tumor stroma." (PMID 25671108, 2014). "The possible role of SDHB in ovarian cancer was investigated in vitro, using proliferation, migration and invasion assays." (PMID 25491408, 2014). "In current study, we aimed to gain a better understanding of the consequences of SDHB alteration by gene silencing or overexpression in human ovarian cancer cell lines." (PMID 25491408, 2014). "Using the SDHB specific siRNA and overexpression plasmid, the expression of SDHB was silenced and conversely induced in ovarian cancer cell lines SKOV3 and A2780, respectively." (PMID 25491408, 2014). "The relationship between SDHB expression and clinical characteristics in human ovarian carcinoma will be determined in our future studies." (PMID 25491408, 2014). "Enhanced SDHB expression inhibited cell proliferation, invasion, migration and promoted apoptosis in human ovarian carcinoma." (PMID 25491408, 2014). "In our study, we aimed to gain a better understanding of the role of SDHB in ovarian carcinoma by gene silencing and over expression." (PMID 25491408, 2014). "Our results firstly revealed that SDHB played a key role in cell proliferation, invasion, migration, and apoptosis of human ovarian carcinoma via AMPK-HIF-1α pathway." (PMID 25491408, 2014). "To explore the role of SDHB in human ovarian carcinoma, we designed plasmid to induce SDHB expression in SKOV3 cells." (PMID 25491408, 2014). "The relationship between SDHB loss and EMT was also shown in colon and ovarian cancer." (PMID 35083212, 2021). "In one patient (ID3) with a pathogenic SDHB variant, we found an additional pathogenic germline variant in CHEK2 (c.1100delC, p.(Thr367fs)) that is known to be associated with hereditary breast and ovarian cancer." (PMID 31212687, 2019). "SDHB silencing significantly promoted ovarian cancer cell proliferation (P < 0.05)." (PMID 25491408, 2014). "Finally, we compared the expression of SDHB between ovarian carcinoma and normal ovarian epithelium tissues." (PMID 25491408, 2014). "SDHB-overexpression might be a potential therapeutic strategy to inhibit tumour progression in human ovarian carcinoma." (PMID 25491408, 2014). "The expression of HIF-1α was strongly elevated in SDHB-silenced ovarian cancer cells." (PMID 25491408, 2014). "Over-expression of SDHB significantly inhibited ovarian cancer cell proliferation." (PMID 25491408, 2014). "On the other hand, p-AMPKα and p-P38 MAPK level were increased in the SDHB-silenced cells, suggesting that SDHB silencing could activate AMPK pathway in ovarian cancer." (PMID 25491408, 2014). "The results showed SDHB affected ovarian cancer progression by altering HIF-1α expression." (PMID 25491408, 2014).
ovarian carcinoma (continued). "Interestingly, SDHB mRNA expression was 36.80% lower in the corresponding metastasis (P < 0.05) than that in the primary ovarian carcinoma tissues." (PMID 25491408, 2014). "Overexpression of SDHB might be an effective therapeutic strategy for treatment of ovarian carcinoma." (PMID 25491408, 2014). "SDHB-overexpression might be a new approach to inhibit tumor progression in human ovarian carcinoma." (PMID 25491408, 2014). "In addition, SDHB mRNA expression was decreased in the corresponding metastasis compared with the primary ovarian carcinoma, suggesting SDHB contributed to tumour metastasis." (PMID 25491408, 2014). "The results suggested SDHB silencing could prevent ovarian cancer cell apoptosis." (PMID 25491408, 2014). "Moreover, SDHB was downregulated by hypoxia mimetic CoCl2 in human ovarian cancer cells." (PMID 25491408, 2014). "However the role of SDHB in ovarian cancer is still unclear." (PMID 25491408, 2014). "An analysis of the TCGA ovarian cancer dataset revealed significant genomic deletions of SDH members in 67% of serous ovarian cancer patient samples, with heterozygous deletion of SDHB found in 39% of the samples." (PMID 25671108, 2014). "In current study, we demonstrated that SDHB played an important role in cellular proliferation, invasion, migration and apoptosis via AMPK-HIF-1α pathway in human ovarian carcinoma." (PMID 25491408, 2014). "Statistically significant focal deletion of SDHB (q < .01) was confirmed in Tumorscape, a dataset that includes whole genome analyses of somatic copy number alterations (CNA) in 110 ovarian cancer samples." (PMID 25671108, 2014). "Immunohistochemical staining of ovarian carcinoma tissue microarray was used to determine levels of SDHB protein in malignant tumor cells relative to adjacent nonmalignant stroma." (PMID 25671108, 2014).
hepatocellular carcinoma (8 papers, 2018 to 2023). A malignant tumor that arises from hepatocytes. "By contrast, SDHB has been reported to suppress tumorigenesis in clear cell renal cell carcinoma, while decreased SDHB accelerates growth in hepatocellular carcinoma (HCC), which is ascribed to a switch from aerobic respiration to glycolysis in HCC." (PMID 36675163, 2023). "Succinate treatment as well as SDHB-silencing has been shown to induce SUCNR1 mRNA and protein expression in human hepatoma cells, suggesting a positive feedback of inappropriate succinate accumulation on expression of its receptor." (PMID 33776908, 2021).
clear cell renal cell carcinoma (7 papers, 2018 to 2025). "SDHB is associated with PGL more often than PCC, with an increased risk of GI stromal tumor and renal clear cell carcinoma." (PMID 37024931, 2023). "Downregulation of SDHB, SDHC, or SDHD is also a common feature of clear renal cell carcinoma, with the loss of cellular SDH activity correlating with invasiveness." (PMID 37119852, 2023).
colon cancer (7 papers, 2017 to 2024). "Levels of SDHB are significantly decreased in human colon cancer tissues, and this is associated with tumor cell dedifferentiation." (PMID 29449614, 2018). "Together with results of a previous study, describing SDHB as a target of miR‐142‐5p in colon cancer, our data indicated that miR‐142‐5p, and thereby Th17 cells, targets three of four subunits of the SDH complex and consequently reduces its activity." (PMID 37899663, 2024). "The authors also demonstrated that SDHB knockdown induces an increase in colon cancer cell invasion and activation of the TGF-beta signaling pathway." (PMID 37239099, 2023). "In vitro experiments conducted by the same authors demonstrated that the knockdown of SDHB in commercial SW1116 colon cancer cells led to the activation of the TGFβ signal pathway." (PMID 37239099, 2023). "Here, we established SDHB knockout cancer cell lines from human colon cancer HCT116 cells using the clustered regularly interspaced short palindromic repeat (CRISPR)/Cas9 knockout system, and clarified its metabolic characteristics." (PMID 28423651, 2017). "In this study, we established SDHB knockout cancer cell lines from the human colon cancer HCT116 cell line, and characterized them to identify vulnerabilities that could be targeted therapeutically in SDHB-deficient cancer." (PMID 28423651, 2017). "Furthermore, the SDHB expression pattern in HCC was similar to that of colon cancer." (PMID 29449614, 2018). "In a study conducted by Wang and co-workers, a decreased expression of SDHB subunit was observed in CRC patients and in commercially available colon cancer cell lines." (PMID 37239099, 2023). "According to the PDC database, compared with normal tissues, SDHA (p < 2.2×10-16), SDHB (p = 1.1×10-13), SDHC (p = 1.2 ×10-10), and SDHD (p = 0.00028) were low expressed in colon cancer at protein level." (PMID 36949947, 2023).
lung carcinoma (7 papers, 2015 to 2025). "On the other hand, circ0515 recruited RNA binding motif protein 45 (RBM45) to stabilize SDHB mRNA, promoting SDHB expression and mitochondrial oxidative phosphorylation and succinate metabolism, leading to increased cisplatin resistance in lung cancer cells." (PMID 40617805, 2025). "Loss of SDHB induces ROS production and subsequently stabilizes HIF-α, promoting osteosarcoma and lung cancer cell growth." (PMID 36717552, 2023). "Collectively, these findings demonstrate that complex II-dependent OXPHOS drives the adaptive response during glutamine deprivation, and the SDHB subunit can be exploited as an indicator of vulnerability to drug resistance in lung cancer." (PMID 35127502, 2021). "Moreover, we found that activation of the circ0515/RBM45/SDHB axis increases cisplatin resistance in lung cancer cells, potentially by enhancing oxidative phosphorylation, reducing cisplatin-induced ROS damage, and inhibiting apoptosis." (PMID 40617805, 2025). "Moreover, SDHB expression is negatively correlated with the prognosis of lung cancer patients, and ROC curve analysis suggested that SDHB can effectively differentiate normal from lung cancer patients." (PMID 40617805, 2025). "Finally, whether the circ0515/RBM45/SDHB signaling axis functions broadly across various cancers or represents a lung cancer-specific mechanism remains unresolved." (PMID 40617805, 2025). "On the other hand, circ0515 synergizes with RBM45 to maintain the stability of the SDHB transcript, increase SDHB protein expression, promote mitochondrial oxidative phosphorylation and succinate metabolism, and ultimately enhance cisplatin resistance in lung cancer cells." (PMID 40617805, 2025). "Further analysis revealed that SDHB is significantly upregulated in lung cancer and that RBM45 expression is significantly positively correlated with SDHB expression in lung cancer." (PMID 40617805, 2025). "Among them, a number of proteins related to mitochondrial biogenesis were upregulated in BrM lesions as compared to paired primary lung cancers, including NDUFAF2, SDHB, COX5A, and ATP5PO." (PMID 39593114, 2024). "Cell proliferation assays showed that the inhibitory effects of circ0515 knockdown on lung cancer cell proliferation could be rescued by overexpression of RBM45 and SDHB, respectively." (PMID 40617805, 2025).
multiple endocrine neoplasia type 2 (7 papers, 2005 to 2022). Multiple endocrine neoplasia type 2 (MEN2) is a multiple endocrine neoplasia, a polyglandular cancer syndrome characterized by the occurrence of medullary thyroid carcinoma (MTC), pheochromocytoma (PCC), in one variant, primary hyperparathyroidism (PHPT). "The whole-life incidence of PH and PGL is high in familial syndromes with these tumors: 1–5% in neurofibromatosis type 1 (NF1), 15–20% in VHL, 30–50% in multiple endocrine neoplasia type 2 (MEN-2), and probably more than 50% in SDHB and SDHD gene mutation carriers." (PMID 17156452, 2006).
sympathetic paraganglioma (7 papers, 2014 to 2024). A benign or malignant paraganglioma arising from the chromaffin cells of the paraganglia that are located along the sympathetic nerves. "In this case, we report a novel somatic SDHB mutation at H244D in a sympathetic paraganglioma presenting as a cardiac mass." (PMID 37908983, 2023).
Hypertension (6 papers, 2012 to 2025). The presence of chronic increased pressure in the systemic arterial system. "We don’t know.”Mother, SF1, T6, SDHB variant in her and her daughter, leading to the discovery of hypertension in the mother)." (PMID 38802530, 2024). "Indeed, treatment with a different inhibitor, sunitinib, led to a reduction in tumor size, stabilization of disease, and improvement in hypertension among SDHB-mutated PHEO/PGL patients, warranting further evaluation of this compound." (PMID 34359671, 2021). "Nineteen SDHB carriers with an HNPGL presented with hypertension (19 of 54, 35 per cent)." (PMID 29951630, 2018).
prostate carcinoma (6 papers, 2019 to 2023). A carcinoma that arises from epithelial cells of the prostate gland. "The inferred subset GRN from the PC3 prostate cancer cell line suggests several genes as suppressors of SDHB, such as PNKB, PWP1, PNP, HADH, HTATSF1, and BAZ1B, among which PWP1, HTATSF1, and BAZ1B are transcription regulators." (PMID 33168813, 2020). "Currently only one case has been reported of prostate cancer SDHB negative at immunohistochemistry, while the association between prostate cancer and PPGLs has not been described." (PMID 34830985, 2021).
hereditary cancer (5 papers, 2018 to 2024). Malignant neoplasms occurring in families at a rate greater than that expected by chance and caused by germline mutations in a specific gene. "Four variants classified as KP or EP in the BRCA2, PMS2, and SDHB genes have been recognized to cause different types of hereditary cancer." (PMID 30217213, 2018). "Additionally, SDHA and SDHB variants have been associated with both mitochondrial complex II deficiency in biallelic form, and hereditary cancer susceptibility in monoallelic form." (PMID 34012134, 2021). "Two (0.8%) patients presented with both a PGL and a PCC, one of whom tested positive for an LPV/PV in a hereditary cancer gene, which happened to be SDHB." (PMID 39539798, 2024).
neuroblastoma (5 papers, 2004 to 2021). Neuroblastoma (NB) is the most common solid, extracranial childhood tumor. "We were unable to demonstrate the previously reported SDHB promoter methylation in the SK-N-SH neuroblastoma cell line using both MS-HRM and methylation-specific PCR (MSP) assays." (PMID 19778456, 2009). "In all, 22% (10 out of 46) of the neuroblastomas demonstrated SDHB CpG island promoter methylation by MSP analysis compared to 0 of 20 normal control blood samples." (PMID 15505628, 2004). "To investigate the possible functional significance of this partial promoter methylation, we screened eight neuroblastoma cell lines and identified two (SK-N-SH and SK-N-AS) with partial SDHB methylation by MSP." (PMID 15505628, 2004). "Direct sequencing of the SDHB coding exons and flanking sequences in 46 neuroblastoma tumours was performed." (PMID 15505628, 2004). "It was observed that a 3-year-old patient diagnosed with primary neuroblastoma carried the germline non-sense mutation in the SDHA gene, while a 5-year-old patient from a Spanish family was diagnosed with carrying a germline deletion in SDHB." (PMID 34768850, 2021). "SDHB promoter methylation status was investigated in 46 primary neuroblastoma tumours." (PMID 15505628, 2004). "Hence, to evaluate SDHB as a candidate neuroblastoma tumour suppressor gene (TSG) we performed mutation analysis in 46 primary neuroblastomas by direct sequencing, but did not identify germline or somatic SDHB mutations." (PMID 15505628, 2004). "We did not detect somatic SDHB gene mutations in neuroblastoma and we could not demonstrate evidence for epigenetic inactivation." (PMID 15505628, 2004). "In neuroblastoma pediatric patients, alterations in the SDHA and SDHB genes have been found." (PMID 34768850, 2021). "We observed similar results using neuroblastoma cell line, where the effect of PL was more prominent in pseudohypoxic cells without the SDHB protein." (PMID 27244895, 2016). "Currently, there is no SDHB-mutated PHEO/PGL cell line available; therefore, we used N2a cells, which are derived from mouse neuroblastoma." (PMID 27244895, 2016).
pituitary cancer (5 papers, 2017 to 2023). A primary or metastatic malignant neoplasm affecting the pituitary gland. "Vacuoles typical of SDHB-mutated PitNETs were identified and again LOH was confirmed in the pituitary carcinoma tissue." (PMID 35938916, 2022).